IL17A (interleukin 17A)
Diseases named in the same sentence as IL17A in open-access papers (continued):
Sharing a sentence is not in itself a finding about the gene and the disease.
COVID-19 (continued). "Nevertheless, another study showed that in paediatric/young COVID-19 patients (n = 65, < 24 years) who generally suffer less severe disease there were increased serum levels of IFNγ and IL-17A but not of IL-6 and TNFα protein compared to adult COVID-19 patients (n = 65)." (PMID 36941580, 2023). "Similarly, TNF and IL-17A were upregulated with COVID-19 in non-pregnant patients and only showed a slight tendency to increase during pregnancy." (PMID 37016066, 2023). "In a cohort study of severe COVID-19 patients (n = 9) it was shown that their BAL contained a clonal expansion of a sub-population of memory Th17 cells that increase the secretion of several pro-inflammatory mediators, such as IL-17A and granulocyte–macrophage colony-stimulating factor (GM-CSF)." (PMID 36941580, 2023). "Both GA/18β doses modulated inflammatory response by reducing mainly IL-17A expression, which in turn kept IL-1β, IL-6, IL-8 and TNF-α interleukins unchanged, indicating significant modulation of key interleukin levels to prevent exacerbation of the immune response in COVID-19 patients." (PMID 38283346, 2023). "In a cohort of 43 COVID-19 patients and 25 healthy controls, circulating MAIT cells displayed reduced frequency and an activated phenotype in individuals with COVID-19, regardless of disease severity, as characterised by high expression of IL-17A, TNFα, CD38, CD69 and HLA-DR." (PMID 34050887, 2022). "Conversely, during the acute phase of SARS-CoV-2 infection, CD4+ T cells from the lungs of patients with COVID-19 did not increase Th17-associated genes, including RORC, IL17A, and IL17F, and CCR6 expression was significantly reduced in patients with severe COVID-19." (PMID 36146622, 2022). "To explore whether the leucocyte response is limited by COVID-19, we stimulated cells with LPS or PMA/Ion, and a clear proinflammatory response with cytokines such as TNF-α, CCL3, CCL4, IL-17a, CCL23 and CXCL8 was detected in the supernatant, indicating that leucocytes are not anergic." (PMID 35901034, 2022). "In addition to these findings, it was observed in the intergroup analysis that the COVID-19 group without SIgA showed higher levels of IL-10, IL-13, and IL-17A than the control group without SIgA." (PMID 35686128, 2022). "Given not all the severe COVID-19 patients had increased IL-17A expression, one may not want to treat all patients with IL-17A inhibitors." (PMID 33603759, 2021). "Although an increased capacity of T cells to produce IL-17A may occur in COVID-19 pneumonia, there was no significant elevation of IL-17A in our COVID-19 patients." (PMID 34367188, 2021). "Therefore, it could be useful to measure IL-17A levels in bronchoalveolar lavage fluid (BALF) and plasma/serum samples of moderate and severe COVID-19 patients." (PMID 33353549, 2020). "Interestingly, as observed in human COVID-19 patients with fatal disease (KO and 1A0) and those with severe disease (6A4) had overall, significantly increased systemic levels of G-CSF, IL-6, IL-10, TNF-α, IL-12 (p40), IL-17A, CCL5, and CCL11 compared to those with moderate disease (6A2 and 1A3)." (PMID 40242753, 2025). "In particular, because the TH17/IL-17 axis has not been linked to protective antiviral immunity, we propose that overproduction of IL-17A and GM-CSF by overactivated TRM17 cells is a feature of severe COVID-19 that might be involved in the immunopathology." (PMID 33622974, 2021). "Besides, we can also see that both IL-8/IL-17A tissue expression and the neutrophil score remain lower in almost all COVID-19 group patients regardless of time from hospitalization to death (11.5; 1–39), which is higher than the H1N1 group (1.5; 1–19); p = 0.002." (PMID 33868301, 2021). "Of the tested inflammatory cytokines/chemokines, the levels of IL-8, IL-17A, and IL-23 were strikingly higher in women with COVID-19 disease and PPH as compared to those with/without COVID-19 but without PPH." (PMID 40303405, 2025).
COVID-19 (continued). "In contrast, COVID-19 negative individuals showed lower-magnitude responses for TNF, IL-10, and IL-17A but exhibited multiple peaks in IL-2, IL-6, and IFN-γ production." (PMID 40406109, 2025). "For TMPRSS2, IL-17A, ADAM-17, and AP, values were significantly higher in all non-healthy groups (previously infected, mild, and severe COVID-19) compared to healthy individuals." (PMID 40003732, 2025). "Specifically, we compared the levels of IFN-γ, IL-6, IL-22, IL-4, IL-8, IL-10, and IL-17A between anti-SARS-CoV-2 IgG-positive and seronegative individuals, all without a history of COVID-19." (PMID 40160814, 2025). "Interestingly, IL-17A levels were decreased in this comparison, but it is important to note that the COVID-19-negative participants are not healthy controls, but participants who were hospitalized for suspected COVID-19 but were found to be negative for SARS-CoV-2." (PMID 39493750, 2024). "The authors also demonstrated that, while IL-17A is not considered a good marker for disease severity, it is capable of activating inflammatory pathways that may result in tissue damage and exacerbation of disease, meaning it likely plays a deleterious role in COVID-19 pathogenesis." (PMID 34050887, 2022). "We investigated the circulating levels of IFNγ, IL-4, sIL-4R, IL-5, IL-9, IL-17A, IL-17F, IL17-E/25, IL-22 and sCD30 in surviving and non-surviving severe COVID-19 patients and healthy controls." (PMID 36142255, 2022). "On the other hand, some markers (i.e., IL-5, IL-7, IL-17A, CXCL8, and VEGF) were increased in critical COVID-19 patients only and not in macrophage activation syndrome." (PMID 35645351, 2022). "Moreover, the association between IL17A/IL17F gene and COVID-19 severity was identified in a regression analysis that include age, sex, and underlying diseases as covariates, suggesting that IL17A/IL17F gene is involved in COVID-19 severity regardless of age, sex and underlying diseases." (PMID 35264675, 2022). "AOSD, but not COVID-19, showed significantly higher IFN-γ and IL-17A compared with HC (both p<0.01)." (PMID 34367188, 2021). "Th17 cytokine IL17A, as well as type I and type II IFN were not detectable in non-stimulated plasma of COVID-19 patients." (PMID 33585507, 2020). "The production of cytokines in COVID-19 patients and CD4+ T lymphocytes isolated from SARS-CoV-2-vaccinated subjects stimulated with a peptide pool predominantly expressed IL-2 and IFN-γ, whereas IL-17A, IL-4, and IL-10 were less frequent and not significant." (PMID 38140191, 2023). "Interestingly, TNFα, IL-27, IL-17A and IL-12 plasma levels of SARS-CoV-2 negative HD patients were in a similar range as in moderate and severe COVID-19 non-HD patients." (PMID 35265078, 2022). "Lastly, the COVID-19 group without SIgA exclusively showed a positive correlation between IL-12p70 and IL-13, whereas the COVID-19 group with SIgA presented positive correlations between the levels of SIgA and IFN-γ, as well as IL-17A." (PMID 35686128, 2022). "Moreover, we found that in vitro exposure of purified T cells from children with COVID-19 to BzATP, a P2X7R agonist and ATP analogue, promotes a substantial decrease in a wide pattern of cytokines produced by stimulated T cells without inhibiting the production of IL-17A." (PMID 35663467, 2022).
atherosclerosis (583 papers, 2009 to 2026). A disease characterized by the build-up of fatty material and calcium deposition in the arterial wall resulting in partial or complete occlusion of the arterial lumen. "Th17 cells and their signature cytokine IL-17A have been increasingly implicated in the pathogenesis of atherosclerosis, yet their precise role remains controversial." (PMID 40948785, 2025). "The IL-17A, produced by Th17 cells, plays a significant role in the development of cardiovascular diseases like atherosclerosis and is associated with age-related vascular endothelial dysfunction." (PMID 40276600, 2025). "In PLWH, IL-17a has been shown to be associated with endothelial dysfunction and is theorized as an important driver of inflammation leading to atherosclerosis." (PMID 39000373, 2024). "IL-17A blockade in apoE-deficient mice shows a reduction in atherosclerosis development and decreases the vulnerability of plaque, which suggests a similar pathway of ACS and uveitis in patients with AS." (PMID 35757729, 2022). "Together with the observations of reduced HGF, PDGBF, MAP2K6, and QDPR, these results suggest that the novel Affibody molecule effectively blocks IL17A and attenuates circulating inflammatory markers and other atherosclerosis-associated proteins." (PMID 35282365, 2022). "In Rip2−/− mice, T cells preferentially polarized toward pathogenic Th17 cells under pathogenic conditions, resulting in increased IL-17A production, which directly led to the significant enhancement in atherosclerosis." (PMID 36211578, 2022). "Neutralization of IL-17A in SOCS3-deficient mice enhanced atherosclerosis development associated with T cell accumulation in the aorta and elevated vascular cell adhesion molecule 1 (VCAM-1) expression." (PMID 33562334, 2021). "Complementary experiments were conducted in murine models, where addition of exogenous IL-17A-stimulated pathological changes associated with increased plaque instability, while IL-17A inhibition resulted in regression of atherosclerosis." (PMID 29675020, 2018). "IL-17A is signature cytokine of Th17 cells associated with inflammatory and autoimmune diseases, and its association with atherosclerosis is still controversial." (PMID 30069429, 2018). "Similar to our findings, several reports suggest an association of IL-17A with lipid metabolic disorders like atherosclerosis." (PMID 26781963, 2016). "IL-17A is involved in many inflammatory processes by promoting Ang II-mediated hypertension and vascular dysfunction, both of which are risk factors for atherosclerosis." (PMID 26245758, 2015). "In animal models, IL17A deficiency was observed to reduce atherosclerosis, decrease the number of macrophages in the atheroma, and inhibit release of monocyte chemoattractant protein 1, IL1b, IL12, and interferon gamma in the plaque." (PMID 28352449, 2014). "Assuming that the severity of atherosclerosis symptoms is associated with the degree of inflammation (active expression of IL-17A), a decreasing percentage of methylation was expected in control subjects, whereas pCAD patients would have the lowest level of methylation, as reported for IL-6 in CAD." (PMID 38132456, 2023). "IL-17A participates in inflammation of blood vessels and cardiac cells and is also implicated in the pathogenesis of cardiovascular diseases that occur prematurely in chronic inflammatory disorders including atherosclerosis and myocardial infarction." (PMID 37880253, 2023). "In this study, apolipoprotein E-deficient (ApoE–/–) mice were fed a high-fat diet to induce atherosclerosis, followed by the treatment with exogenous recombinant IL-17A or the neutralizing antibody to confirm the impact of IL-17A on the established atherosclerotic plaques." (PMID 36133421, 2022). "In spite of this known role of the IL-17A in the development of atherosclerosis, only one study has explored whether IL-17A gene variation plays a role in susceptibility to coronary artery disease." (PMID 25615631, 2015).
atherosclerosis (continued). "Moreover, IL-17A is involved in the pathogenesis of cardiovascular diseases, such as atherosclerosis and acute coronary syndrome and in the cardiovascular risk associated with systemic immunological disorders." (PMID 24940514, 2014). "Therefore, the aim of this study was to evaluate the DNA methylation status of the IL-17A gene promoter to establish whether it may represent a risk factor for subclinical atherosclerosis (SA) or clinical coronary artery disease (CAD)." (PMID 38132456, 2023). "The relevant literature suggests that IL-17A is significantly expressed in carotid plaques and that the development of atherosclerosis is reduced by the inhibition of IL-17A." (PMID 40165931, 2025). "In recent years, an increasing number of studies have shown that Th17 and IL-17A promote the onset and development of atherosclerosis." (PMID 37884768, 2024). "Neutralizing IL-17A blocked atherosclerosis progression in Apoe -/- mice on a high-fat diet, and inhibiting CD4+ T cell polarization slowed coronary disease progression." (PMID 39723414, 2024). "Considering the potential role of IL-17A in atherosclerosis and even MI, it is understandable why IL-17 has been considered a promising target for both controlling PsO and PsA disease activity and reducing cardiovascular risks." (PMID 38910708, 2024). "The findings of our study suggest a possible link between elevated levels of IL-17A and subclinical atherosclerosis." (PMID 39104857, 2024). "Recently, experimental researches showed that Th17 cells and IL-17A play an important role in promoting stroke pathogenesis (atherosclerosis), inducing secondary damage after stroke, and regulating post-stroke repair." (PMID 37884768, 2024). "Interleukin-36 (IL-36) is increasingly recognized as a pivotal trigger in the production of interleukin-17A (IL-17A) within the skin, which in turn plays a crucial role in the development of atherosclerosis, a major contributor to cardiovascular disease." (PMID 38892457, 2024). "IL-17A is also involved in the development of atherosclerosis, hypertension, and atrial fibrillation by promoting water and sodium retention and altering myocardial electrophysiology." (PMID 38750443, 2024). "IL-17A epigenetic research is particularly scarce and, as far as we know, this is the first study with an approach related to asymptomatic atherosclerosis." (PMID 38132456, 2023). "IL-17A expression is upregulated in atherosclerosis and pathophysiologically contributes to atherosclerosis by increasing plaque size and aggravating inflammation." (PMID 37623290, 2023). "When the IL-17A gene expression is attenuated by an increased methylation in a subject with atherosclerosis, it is likely that the disease progression is retarded." (PMID 38132456, 2023). "After 5 weeks, the IL-17 injection greatly exacerbated aortic root plaque formation, confirming that IL-17A exacerbated atherosclerosis development in vivo." (PMID 36211578, 2022). "IL-17A/IL-17A receptor blockade has also been shown to ameliorate the symptoms of other disorders such as atherosclerosis, inflammation-sensitised encephalopathy and anklyosing spondylitis." (PMID 34505185, 2022). "The therapeutic drug digoxin for atherosclerosis is a direct antagonist of RORγt which is the main transcription factor of IL-17A." (PMID 35371044, 2022). "In this study, we investigated the effect on pro-inflammatory mediators and atherosclerosis development of an Affibody molecule that targets IL17A." (PMID 35282365, 2022). "The same models were treated with an anti-IL-17A monoclonal neutralizing antibody (IL-17mAb group) to confirm the role of IL-17A in atherosclerosis." (PMID 36133421, 2022). "The treatment of atherosclerosis with digoxin can significantly reduce the circulating lipid, the expression level of IL-17A and the size of lesions in Apoe -/- mice, suggesting that reducing IL-17A is beneficial." (PMID 35371044, 2022).
atherosclerosis (continued). "The IL-17 family has six members, labeled IL-17A-F, of which IL-17A is the most studied isoform and is involved in atherosclerosis." (PMID 36133421, 2022). "Increasing evidence shows that IL-17A is critically involved in atherosclerosis, autoimmune disease and angiogenesis." (PMID 34440624, 2021). "Several groups have reported the presence and accumulation of IL-17A-producing cells during atherosclerosis progression." (PMID 33562334, 2021). "TH17 cells produce IL-17A and -F, both of which induce pro-inflammatory cytokines, and IL-17A blockade reduces experimental atherosclerosis." (PMID 35087883, 2021). "The role of IL-17A in atherosclerosis has been extensively investigated; however, it still remains debatable." (PMID 33562334, 2021). "Consistently, another study showed significantly more atherosclerosis and vulnerable plaque phenotype in IL-17A−/−ApoE−/− mice." (PMID 32849502, 2020). "IL-17A has been shown to be involved in the pathogenesis of lipid metabolism and atherosclerosis, suggesting that IL-17A has a role in the pathogenesis of PCOS." (PMID 31906930, 2020). "On the other hand, there is strong evidence that IL-17A plays a role in the pathogenesis of atherosclerosis." (PMID 30862094, 2019). "Interleukin-17A (IL-17A), a member of the IL-17 cytokine family (IL-17A to IL-17F), has been demonstrated to paly crucial role in the progress of atherosclerosis." (PMID 29262579, 2017). "High concentration of IL-17A in atherosclerotic plaques can promote the development of atherosclerotic lesions, while blockade of IL-17A in atherosclerosis mice model resulted in a significant reduction of atherosclerotic lesions." (PMID 29262579, 2017). "Pro-inflammatory IL-17A-producing T cells are present in the adventitia and blockade of IL-17A leads to reduction of macrophage accumulation and atherosclerosis." (PMID 28838042, 2017). "Several lines of evidence both in animal models and in humans have shown that IL-17A is involved in atherosclerosis." (PMID 25615631, 2015). "Several recent studies have reported that the IL-17A level increases in cases of atherosclerosis and vascular inflammation, and that such increases contribute to progression of inflammation." (PMID 25273526, 2014). "IL17A concentration has been studied for several years, and its involvement in atherosclerosis has been investigated." (PMID 28352449, 2014). "Studies in ApoE−/− mice genetically deficient for IL-17 or treated with anti-IL-17A antibodies demonstrated that absence or depletion of IL-17 attenuated development of atherosclerosis." (PMID 25352848, 2014). "IL-17A is also involved in atherosclerosis; furthermore, in humans a positive correlation has also been found between circulating IL-17A levels and acute coronary syndrome." (PMID 24940514, 2014). "In the same study, administration of an anti-IL-17A antibody accelerated atherosclerosis, indicating a protective role for TH17 cells." (PMID 25352848, 2014). "The role of IL-17A in atherosclerosis remains controversial, with different studies suggesting either a proatherogenic or an atheroprotective role." (PMID 24455725, 2013). "Anti-CD20 treatment was associated with an increase in the percentage of IL-17+ T cells (Th17 cells), and IL-17A neutralization abrogated anti-CD20 attenuation of atherosclerosis." (PMID 23248624, 2012). "Finally, the impact of IL-17A inhibition (IL-17Ai) on PV and atherosclerosis (assessed by carotid Doppler color ultrasound) was evaluated using a prospective intervention study." (PMID 42058202, 2026). "The pro-atherogenic role of IL-17A has been confirmed by multiple experiments, and future studies are needed to further prove whether CTLA-4 inhibition can influence the progression of atherosclerosis through the CXCR4/Th17/IL17A axis." (PMID 40821806, 2025).